IL6 (interleukin 6)
Diseases named in the same sentence as IL6 in open-access papers (continued):
Sharing a sentence is not in itself a finding about the gene and the disease.
depression (continued). "A recent meta-analysis investigating children and adolescents with depression has found that IL-6 predicts the future development of depression and conversely that the establishment of depression is a significant predictor of IL-6 increase." (PMID 34367160, 2021). "In animal models of depression, IL-6 (and/or IL-1β appears to be instrumental for the development of chronic stress and depression-like behaviors." (PMID 34367160, 2021). "A study examining 66 patients undergoing hematopoietic stem cell transplantation showed that those with depression had a higher ratio of IL-6/IL-10 than controls." (PMID 33810574, 2021). "Depression has been recently demonstrated to induce neuropeptide Y expression by PCa cells through sympathetic activation, resulting in IL-6 release from TAMs and subsequent intratumoral MDSC infiltration." (PMID 33800156, 2021). "IL-6 is a commonly investigated protein and a well-known biomarker of inflammation, stress, and depression, all closely interrelated, in both preclinical and clinical studies." (PMID 34765010, 2021). "Prospective researches also show that depression can predict the later level changes of IL-6 and CRP." (PMID 34054732, 2021). "In Ps patients with comorbid depression, high serumconcentrations of IL-6 and IL-18, as well as IL-17A, were presumed to act as sharedinflammatory mechanisms." (PMID 34819201, 2021). "We also examined the effect of CSDS on PFC microglial cytokine expression, including IL‐1β, TNF‐α, and IL‐6, as those are reportedly increased in the cerebrospinal fluid and/or peripheral blood of patients with depression." (PMID 34043886, 2021). "Patients with depression showed increased levels of IL-8, IL-10, IL-12, and IL-13, whereas IL-6 and TNF-α showed mixed results between studies." (PMID 33578686, 2021). "It is known that TNF-α, similarly to IL-6, is engaged in the occurrence of cancer cachexia and depression." (PMID 34681685, 2021). "Such cognitive impairment is induced by the reaction of IL-6 with other factors or via subsequent pathological issues such as depression." (PMID 34299040, 2021). "The levels of pro-inflammatory cytokines (IL-1β and IL-6) are increased in some brain regions of patients with depression." (PMID 34051074, 2021). "IL-6 knockout mice exhibit resistance to stress-induced depression-like behavior and showed reduced despair in FST and TST." (PMID 34875999, 2021). "We used data from the ALSPAC birth cohort to examine temporality and specificity of association of IL-6 and CRP levels at age 9 and risks for psychosis and depression at age 24, addressing some of the key gaps in the literature." (PMID 33684738, 2021). "Depression increases the production of several inflammatory cytokines, including IL-1, IL-6, and interferon-gamma." (PMID 34711196, 2021). "Peripheric inflammation activation such as the increased levels of IL‐1β, IL‐6, and interferon‐γ are found in depressive patients or animal model of depression." (PMID 34492157, 2021). "In people with MS with comorbid fatigue and/or depression, there are reported increased serum and CSF concentrations of the pro-inflammatory cytokines, such as interleukins (IL-1a, IL-1b, IL-2, IL-6), TNF-α and IFN-γ." (PMID 35242093, 2021). "The FMT from HV suppressed colon shortening, reduced myeloperoxidase activity, and IL-6 expression in the colon of mice with the IBD/D+-F-induced depression." (PMID 34650107, 2021). "Higher IL‐6 circulating levels in childhood can predict greater risk for depression later in life, indicating that IL‐6 is a promising biomarker for diagnosing and predicting depression." (PMID 31421056, 2021). "Depression displays strong relation to an increase in peripheral inflammatory mediators, such as IL-6, C-reactive protein and TNF-α." (PMID 34200513, 2021).
depression (continued). "A 2 year South Korean longitudinal study presented various correlations between five proinflammatory cytokine levels (TNF-α, IL-1α, IL-1β, IL-6, and IL-8) and late-life depression (LLD) from cross-sectional and prospective perspectives." (PMID 34299040, 2021). "A wide body of work has associated major depressive disorder with low-grade elevations in inflammatory markers like CRP, IL-6, and TNF-a." (PMID 33831008, 2021). "In conjunction with measures of pregnancy-specific anxiety and depression, serum biomarkers (IL-2, IL-6, IL-10, IL1-B, TNF-α, CRH, CRP, and cortisol) were analyzed for each trimester throughout pregnancy." (PMID 34360332, 2021). "It is known that pro-inflammatory cytokines are sufficient to induce symptoms of depression in patients and that IL1β as well as IL6 play a prominent role in this mechanism." (PMID 33580474, 2021). "Among the biochemical changes assessed, in this study, and were found to be associated with depression are the increased serum of TNF-α and IL-6." (PMID 34336111, 2021). "Two meta-analyses showed reliably higher levels of inflammatory markers in depression, namely IL-1β, IL-6, C-reactive protein (CRP), and TNF-α." (PMID 34975571, 2021). "Genetically-predicted concentration/activity of IL-6 and CRP were associated with both depression and anxiety." (PMID 34505025, 2021). "Large meta-analyses report cross-sectional and longitudinal associations between inflammatory markers - such as C-Reactive Protein (CRP) and Interleukin 6 (IL-6) - and depression." (PMID 34135474, 2021). "As already discussed, depression in MS has been associated with increased levels of TNF-α, interleukin 1β (IL-1β) and interleukin 6 (IL-6) in both CSF and blood." (PMID 33922780, 2021). "The aim of the present narrative review is to elucidate the fundamentals, implications, challenges of cytokine research specifically IL-6 in major depressive disorder." (PMID 33593388, 2021). "While not differing between metyrapone and placebo groups, participants with higher pre-treatment IL-6 tended to have more severe depression at the end of the trial." (PMID 33669254, 2021). "Activated microglia are a major source of proinflammatory cytokines, including IL-1, IL-6, and IL-12 release in depression." (PMID 33144710, 2021). "Chronic unpredictable mild stress can induce depression in mice and increase serum cytokines such as IL-1β, IL6, and TNFα." (PMID 34082798, 2021). "For example, the severity of depression in patients with RA (as evaluated with the Hospital Anxiety and Depression Scale) is significantly correlated with blood levels of IL-6 and IL-17 in patients with RA." (PMID 34715926, 2021). "Circulating markers of inflammation such as interleukin-6 (IL-6) and C-reactive protein (CRP) are associated with depression and CVD in adults." (PMID 34146903, 2021). "Secondary outcomes were inflammation parameter (interleukin-6), stress, anxiety, depression, quality of life, and fatigue at week 5, and sleep quality, stress, anxiety, depression, quality of life, and fatigue 17 and 29 weeks after randomization." (PMID 34439234, 2021). "Previous meta-analysis noted an increase in proinflammatory cytokines (TNFα and IL-6) in people with depression." (PMID 33919670, 2021). "Similar to IBS, exogenous IL-6 in myenteric plexus also facilitates contraction of proximal colon in chronic unpredictable mild stress (CUMS) induced depression model, coinciding with the higher level of IL-6 in depressed patients." (PMID 33390844, 2021). "Somatic symptoms of both depression and anxiety especially correlate with high levels of inflammatory markers, including IL-6." (PMID 34945157, 2021). "IL-6 is closely related to hypothalamus pituitary adrenal axis hyperactivity, serotonin metabolism disorder, fatigue, anorexia, depression, and autonomic nervous system symptoms." (PMID 34479552, 2021).
depression (continued). "Ketamine, which has demonstrated efficacy in cases of chronic, treatment-resistant depression, exhibits a broad spectrum of anti-inflammatory effects (e.g., TNFα and IL-6 inhibition) in both clinical and preclinical studies." (PMID 33935636, 2021). "LPS can increase the level of IL-1β and IL-6 in prefrontal cortex and lead to depression-like behavior in rats." (PMID 34079622, 2021). "In conclusion, the daily consumption of LcS for 9 weeks appeared to relieve constipation and improve the potentially depressive symptoms in patients with depression and significantly decrease the IL-6 levels." (PMID 34209804, 2021). "Women suffering from major depression were shown to have a dysregulation of immune mediators such as rise of pro-inflammatory cytokines IL-1ß, IL-6 and decrease in anti-inflammatory cytokines such as TGF-ß." (PMID 35233270, 2021). "The most commonly involved inflammatory markers observed in the pathogenesis of both depression and Psoriasis are IL-6, IL-17, IL-13, IL-23, IL-10, IL-1β, and type A cytokines (TNF-α, IL-2, INF-γ) through Th1 and Th17 lymphocytes mediated processes." (PMID 34183985, 2021). "Concentrations of C-reactive protein (CRP), interleukin 6 (IL-6) and other inflammatory markers are elevated in people with depression and anxiety compared to controls, but evidence for disorder-specificity, linearity and potential causality is sparse." (PMID 34505025, 2021). "In the present study, the levels of Il-6, TNFα, and corticosterone were quantified in the sera of LPS induced depression mice." (PMID 34790666, 2021). "Similar to the previous cytokine study of adults, increased levels of IL-6 were found in cases of pediatric depression and decreased after treatment." (PMID 34576215, 2021). "For example, chronic stress disrupts BBB integrity, promoting peripheral IL-6 to enter into brain parenchyma and resulting in depression-like behaviors." (PMID 34975477, 2021). "Our findings are similar to the results reported in a previous mouse study, which concluded that treatment with NVP-1704 led to the alleviation of depression/anxiety, changes in serum IL-6 levels, and an altered gut microbiome." (PMID 34444820, 2021). "We found that LPS administration induced significant elevation of TNF-α, IL-1β, and IL-6 inflammatory cytokines levels, while these have been reported to contribute to the pathogenesis of depression." (PMID 34207497, 2021). "Some inflammatory factors, such as IL-6 and TNF-α, affect the risk of suicide in patients with depression by impacting the serotonergic system." (PMID 34789194, 2021). "For example, studies have found that the concentrations of IL-6 and C-reactive protein are increased in serum or plasma of depressed individuals, and are significantly correlated with the severity of depression." (PMID 34531719, 2021). "A number of studies reported people with depression to have higher levels of circulating proinflammatory cytokines, interleukin-1β (IL1β) and TNFα and interleukin-6 (IL-6)." (PMID 33919670, 2021). "In both men and women, increased circulating levels of IL‐6 at 9 years old predicts greater likelihood of developing depression by the age 18 (Khandaker, Pearson, Zammit, Lewis & Jones, 2014)." (PMID 31421056, 2021). "IL-6 is a multi-functional cytokine, which is the basis for various immune responses and acute phase reactions, and it is related to depression and autonomic nervous system symptoms." (PMID 34479552, 2021). "For instance, lower Trp levels in patients with depression are known to be inversely correlated to serum concentrations of IL-6." (PMID 34072767, 2021). "Third, using a longer follow-up, we confirm that the effects of childhood IL-6 on risks for psychosis and depression persist longer into adulthood, to a period when most cases of psychiatric disorders emerge." (PMID 33684738, 2021).
depression (continued). "Actually, our previous study on the relationship between the levels of inflammation cytokines and major depressive disorder had already found that MDD patients showed elevated IL-6 level." (PMID 34646171, 2021). "Our findings that levels of CRP and IL-6 are predictive of minocycline response in depression are consistent with existing evidence." (PMID 33504955, 2021). "Studies have shown that AKT1, VEGFA, ESR1, IL6, and AR play an important role in the treatment of depression." (PMID 34257681, 2021). "Younger adults suffering from depression present a significant decrease in the peripheral levels of IL-6, TNF-α, IL-10, and MCP1 after pharmacological treatment with antidepressants." (PMID 35002817, 2021). "We reported that treatment with dietary flavonoids attenuates neuroinflammation in a mouse model of stress-induced depression through regulation of IL-6 secretion." (PMID 33446652, 2021). "We report evidence in support of potential causal associations of several immunological proteins/traits with schizophrenia, and of IL-6 with depression." (PMID 34280516, 2021). "Numerous clinical studies have also shown that the increased circulation levels of inflammatory markers such as IL-6 and/or CRP are associated with depression only in males or more strongly in males than females." (PMID 33672958, 2021). "Some cytokines, such as IL-1β in urine and IL-6 and IL-8 in plasma, have been shown to be elevated in samples taken from women who reported symptoms of depression in the postnatal period." (PMID 34877551, 2021). "It has been widely reported that the up-regulated pro-inflammatory cytokines, such as tumor necrosis factor-α (TNF-α), interleukin-6 (IL-6) and IL-1β are related to depression/anxiety-like behaviors." (PMID 34977127, 2021). "The harsh conditions incurred during cancer treatment (chemotherapy and radiation) has been correlated with the increase of inflammatory mediators such as C-reactive protein (CRP) and interleukin (IL)-6, which can promote depression." (PMID 34371931, 2021). "It is well established that patients with depression and anxiety have higher plasma levels of C-reactive protein and proinflammatory cytokines (e.g., TNFa, IL-1a, IL-1b, IL-4, IL-5, IL-6, IL-12, and interferon)." (PMID 33802143, 2021). "Increased levels of IL-6 are relatively common findings when looking at cytokine levels in patients with depression." (PMID 33578686, 2021). "Schwieler showed that in patients with unipolar treatment-resistant depression, IL-6 plasma levels and the QUIN/KYNA ratio in the plasma significantly increased compared to healthy volunteers." (PMID 34072767, 2021). "Considering these limitations, higher levels of IL-6 have been observed among those with treatment-resistant depression, and among stroke survivors with depression." (PMID 34765010, 2021). "An experimental study showed that XPJYD reduced the serum and hippocampal levels of IL-6, TNFα, and other inflammatory factors in depression model rats and improved their learning and memory behaviors." (PMID 34257681, 2021). "One study found a positive correlation between the decreased interleukin-6 (IL-6) plasma levels and the decreased depression severity induced by PE." (PMID 33430399, 2021). "In future, further RCTs of immunotherapies including anti-IL-6 treatment for depression and psychosis with careful patient selection criteria are required." (PMID 33684738, 2021). "For example, increased peripheral or central IL6 levels contributes to stress reaction and depressive disorder for which tocilizumab (antibody against IL6) mediated therapy can be a strategy to reduce the IL6 activity." (PMID 33820928, 2021). "Preclinical and clinical studies present strong evidence that inflammation is altered in a subset of patients with MDD and there is mounting body of literature for the role of pro-inflammatory cytokines namely IL-6 in pathophysiology of depression." (PMID 33593388, 2021).
depression (continued). "Pro-inflammatory cytokines, including IL-1β, IL-6, IL-12, TNF-α, and IFN-γ, are thought to be associated with depressive disorders." (PMID 34576215, 2021). "In combined models of pain and depression, increases in the cytokines IL-1β and IL-6 in the amygdala have also been noted." (PMID 32849076, 2020). "Report indicated that patients on maintenance hemodialysis (HD) with symptoms of depression had higher serum IL-6 levels." (PMID 32235786, 2020). "Among all inflammatory cytokines, an increased concentration of IL-6 is probably the most widely and consistently reported in depression." (PMID 33255237, 2020). "Multiple therapeutic targets were mediated by active ingredients of XYS, such as IL2, IL4, IL6, IL10, and STAT3, which are involved in immune and inflammatory responses closely associated with depression." (PMID 32256358, 2020). "Depression-like behavior in rodents correlates with increased levels of pro-inflammatory cytokines: interleukin-1β (IL-1β), interleukin-6 (IL-6), and tumor necrosis factor α (TNFα), and decreased levels of anti-inflammatory interleukin-10 (IL-10)." (PMID 32188010, 2020). "For example, co-morbid major depression moderates the association between OCD and raised IL-6 serum levels." (PMID 33041996, 2020). "In particular, some studies have demonstrated an increase in pro-inflammatory markers, such as NF-kB, IL-1 and IL-6, in anxiety- and depression-related conditions." (PMID 31959947, 2020). "Other studies have also found a longitudinal association between circulating IL-6 and CRP levels and risk of depression at follow-up." (PMID 31707310, 2020). "The moderately elevated serum concentration of IL-6 in aged people plays a significant role in functional impairment, including low locomotion, cognitive and mental functions, and depression." (PMID 33114676, 2020). "Mendelian randomization analyses suggested that triglycerides, interleukin-6 (IL-6), and C-reactive protein (CRP) are likely causal risk factors for depression." (PMID 30886334, 2020). "Third, accumulating evidence indicates that depression is related to a state of chronic low-grade inflammation, with significantly increased levels of interleukin (IL)-1, IL-6, tumor-necrosis factor (TNF)-alpha and C-reactive protein (CRP)." (PMID 32228541, 2020). "All this evidence strongly supports that restoring IL-6 activity is the key to treating depression involving inflammation." (PMID 32235786, 2020). "A study found that the IL-6 levels increased during the acute phase of the disease, especially when depression is detected." (PMID 32235786, 2020). "Evidence from animal as well as clinical studies have indicated that increased peripheral or central cytokine interleukin-6 (IL-6) levels play an important role in stress reaction and depressive disorder, especially physical disorders comorbid with depression." (PMID 32235786, 2020). "The underlying mechanisms involve in two pathways, the HPA axis and neurotransmitter metabolism, both of which are affected by increased IL-6 in depression." (PMID 32714875, 2020). "The Sobel test indicated that TS total score was a significant mediator of the influence of CSA on log IL-6 level among participants with depression (z = -2.2, p = 0.02)." (PMID 32413063, 2020). "These pathways are linked to the core genes chiefly including FOS, IL6, TNF-α, Bcl-2, c-Jun, ERK, and EGF gene in our research in the treatment of depression." (PMID 32997725, 2020). "There is strong evidence that depression is accompanied by an increase of proinflammatory cytokines e.g., interleukin-1 (IL-1), IL-2, IL-6, tumor necrosis factor-α (TNFα), and acute phase proteins." (PMID 33324599, 2020). "The present study aimed to examine the impact of CSA on inflammatory biomarkers (IL-6 and IL-1β) in adults with depression and the mediating role of trust." (PMID 32413063, 2020).